HSPB1 (heat shock protein family B (small) member 1)
Diseases named in the same sentence as HSPB1 in open-access papers (continued):
Sharing a sentence is not in itself a finding about the gene and the disease.
breast cancer (continued). "Next, breast cancer cells transfected with an empty vector or with HSPB1 overexpressing vector were treated with 100 μg/ml cycloheximide (CHX, a protein synthesis inhibitor)." (PMID 37454220, 2023). "In particular, HSPB1 promoted migration and invasion in breast cancer cells, modulated EMT of lung cancer cells, and promoted EMT in prostate cancer." (PMID 35936690, 2022). "Silencing HSPB1 in breast cancer cells can enhance the cytotoxicity of CD8+ T cells and their transformation into memory cells." (PMID 33611848, 2021). "Artificial overexpression of HspB1 increased doxorubicin resistance of breast cancer cells, cisplatin and doxorubicin resistance of testis tumor cells, and 17-AAG resistance of cervical cancer cells." (PMID 32927696, 2020). "Studies have shown that overexpression of HspB1 promotes cell proliferation and growth of breast cancer cells in vitro." (PMID 32927696, 2020). "Recently, several studies have indicated that phosphorylation of HspB1 increases apoptosis in leukemia cells, and phosphorylation of both HspB1 and HspB5 increases apoptosis in breast cancer cells." (PMID 32927696, 2020). "HSPB1 has been reported to play an important role in UM micrometastasis and acts as switch between tumor dormancy and tumor progression in breast cancer." (PMID 33050649, 2020). "Initially, HspB1 was reported to promote the invasion of breast cancer cells by upregulation of MMP-9 expression but decrease the motility of breast cancer cells." (PMID 32927696, 2020). "There are also reports linking HspB1 to the maintenance of CSC phenotypes in breast cancer stem cells and gynecologic cancer stem cells." (PMID 32927696, 2020). "Heat shock proteins showed the most significant change of all the upregulated domains, with Hsp90AA1, Hsp90AB1, TRAP1, HspA5, HspB1, HspE1, HspD1, HspA1B, HspA8, HspA9, and HspA4 identified in breast cancer tissue." (PMID 31921692, 2019). "Multiple heat shock proteins, including Hsp90AA1, Hsp90AB1, TRAP1, HspA5, HspB1, HspE1, HspD1, HspA1B, HspA8, HspA9, and HspA4, were significantly upregulated in breast cancer tissue." (PMID 31921692, 2019). "Hsp90AA1, Hsp90AB1, TRAP1, HspA5, HspB1, HspE1, HspD1, HspA1B, HspA8, HspA9, and HspA4 were validated as potential biomarkers for breast cancer tissue." (PMID 31921692, 2019). "In vivo, serum HSPB1 was observed increased in pancreatic carcinoma, hepatocellular carcinoma, breast cancer and gastric adenocarcinoma patients." (PMID 28468249, 2017). "A 4 bp deletion was found in the‏ intron 2 of the Hspb1 gene in the three cat mammary‏ tumors (CP7, CP16, CP28), which is homozygous in‏ two (CP7, CP28), and heterozygous in one neoplastic‏ tissue, as well as the blood of one animal (CP16,‏ CP16b) samples." (PMID 28959337, 2016). "Felipe Zoppino’s poster was titled “Regulation of HSPB1 (HSP27) by has-miR-214 in Breast Cancer” (D.R. Ciocca laboratory, Argentina)." (PMID 26847234, 2016). "Total 180 cats were screened on the basis of Hspb1 4 bp deletion locus (1514-1517del4) which was observed in six mammary tumor cases in Siamese cat breed." (PMID 28224005, 2016). "Crucial effect of phosphorylation has also been observed in Her-2/neu positive breast cancers, where serine 78 phosphorylated HspB1 correlates with Her-2/neu status and lymph node positivity." (PMID 24514166, 2014). "For example, in MCF-7 breast cancer cells exposed to doxorubicin, survival cells are those that overexpress HspB1 consequently of the increased activity of the POU4F2/Brn-3b transcription factor." (PMID 24514166, 2014). "In that respect, HspB1 participates in the maintenance of breast cancer stem cells through regulation of EMT and NF-κB transcription factor." (PMID 24514166, 2014). "In human breast cancer cells expressing high levels of HspB1, the interaction of PTEN with this chaperone further enhances the survival of these pathological cells." (PMID 24514166, 2014).
breast cancer (continued). "A recent striking example is the promoting effect of HspB1 in breast cancer cells to metastasize and grow in the skeleton as bone tumours." (PMID 24514166, 2014). "Of particular interest, elevated levels of HspB1 have also been detected in several cancer stem cells, such as those from lung and breast cancers." (PMID 24514166, 2014). "More recently, it was shown that, in human breast cancer cells, HspB1 increases Her-2/neu protein stability through its ability to chaperone this receptor." (PMID 24514166, 2014). "The elevation of HSPB1 levels could be a significant factor in the advancement of breast cancer and its resistance to chemotherapy." (PMID 39135991, 2024). "We also analyzed the expression level of HSPB1 in breast cancer tissues with different responses to chemotherapy using several public breast cancer datasets, and the results showed that HSPB1 mRNA is upregulated in the majority of chemo-resistant breast cancer tissues." (PMID 37454220, 2023). "According to these findings, HSPB1 may be a prognostic biomarker for breast cancer and may facilitate the development of targeted precision oncology." (PMID 37268925, 2023). "Accordingly, we further evaluated whether HSPB1 could modulate the infiltration of macrophages in breast cancer." (PMID 37454220, 2023). "Subsequently, our results revealed that HSPB1 could promote breast cancer proliferation, migration, invasion, and doxorubicin resistance." (PMID 37454220, 2023). "To gain insight into the intricate molecular mechanism by which HSPB1 regulated doxorubicin-induced ferroptosis, we first explored whether HSPB1 was able to regulate NF-κB pathway to exhibit a tumor-promoting role in breast cancer." (PMID 37454220, 2023). "Furthermore, Kaplan–Meier analysis showed that breast cancer patients with high HSPB1 expression had poorer overall survival and disease-free survival based on the analysis of 131 cases of breast cancers." (PMID 37454220, 2023). "In the present study, we substantiated that HSPB1 could prevent breast cancer cells from chemotherapy-induced ferroptosis, and exhibited a significant role in mediating the progression and chemoresistance of breast cancer." (PMID 37454220, 2023). "We believe that this study has identified HSPB1 as a therapeutic target for breast cancer." (PMID 37268925, 2023). "In conclusion, our results uncovered that HSPB1 is a significant drug-resistant factor, which could inhibit chemotherapy-induced ferroptosis in breast cancer through promoting the activation of NF-κB signaling pathway." (PMID 37454220, 2023). "Therefore, we further evaluated the effect of HSPB1 on breast cancer cell resistance to doxorubicin." (PMID 37454220, 2023). "Western blot assay revealed that HSPB1 overexpression led to decreased expression of epithelial markers (E-cadherin) and increased expression of mesenchymal markers (Fibronectin, N-cadherin, Vimentin), highlighting the significant effect of HSPB1 on regulating EMT in breast cancer cells." (PMID 37454220, 2023). "In addition, HSPB1 expression was increased in the breast cancer cell lines SK-BR-3, T47D, MDA-MB-231, MDA-MB-453, and BT474, especially in SK-BR-3 and MDA-MB-231 cells, compared with that in normal breast MCF10A cells." (PMID 37268925, 2023). "Additionally, HSPB1 interferes with bone metastasis in breast cancer and modulates the PTEN levels in human breast cancer cells." (PMID 37268925, 2023). "HSPB1 overexpression led to decreased expression of IKβ-α (a negative regulator of NF-κB) and increased expression of NF-κB, p-IKβ-α, and downstream molecules of NF-κB (Twist1, IL6, and Survivin) in breast cancer cells, indicating the potential role of HSPB1 in regulating NF-κB activity." (PMID 37454220, 2023). "Collectively, these observations indicated that HSPB1 could aggravate the progression of breast cancer through promoting IL6 secretion." (PMID 37454220, 2023).
breast cancer (continued). "Here, we found that HSPB1 could promote the nuclear translocation and activity of NF-κB in breast cancer cells, as determined by the elevated expression of its target genes." (PMID 37454220, 2023). "The supernatants from HSPB1 overexpressing cells led to increased migration ability of breast cancer cells and tube formation of HUVECs, while the supplement of IL6 neutralizing antibodies could partly attenuate the promoted effect." (PMID 37454220, 2023). "The findings collectively support the hypothesis that HSPB1 is highly expressed in patients with breast cancer." (PMID 37268925, 2023). "Moreover, functional experiments verified that HSPB1 showed a crucial role in the progression of breast cancer." (PMID 37454220, 2023). "Therefore, we adopted a systematic and comprehensive approach to investigate the correlation between HSPB1 expression and clinicopathological features of breast cancer, as well as determine its prognostic value." (PMID 37268925, 2023). "Given the obvious effect of HSPB1 on the expression of IL6 in breast cancer cells detected by our above results, we further investigate whether the secretion of IL6 could be influenced by HSPB1." (PMID 37454220, 2023). "The chi-square test was used to evaluate the correlations between HSPB1 expression and clinicopathologic features of breast cancer patients, such as age, tumor stage, LN metastasis, distant metastasis, histologic grade, ER status, PR status, HER-2 status, and Ki67 expression." (PMID 37454220, 2023). "Collectively, these results indicated that HSPB1 acted as a tumor promoter in breast cancer cells." (PMID 37454220, 2023). "Furthermore, HSPB1 facilitated doxorubicin (DOX) resistance through protecting breast cancer cells from drug-induced ferroptosis." (PMID 37454220, 2023). "Consistently, our results also demonstrated that HSPB1 could bind with IKβ-α and promote ubiquitination-mediated IKβ-α degradation, leading to enhanced nuclear translocation and activity of NF-κB in breast cancer cells." (PMID 37454220, 2023). "Next, we studied the effect of HSPB1 on breast cancer cell apoptosis using flow cytometry." (PMID 37268925, 2023). "Collectively, our study demonstrated that HSPB1 has prognostic value for clinical outcomes and may serve as a therapeutic biomarker for breast cancer." (PMID 37268925, 2023). "In addition, HSPB1 expression was more abundant in most breast cancer cells compared to normal cell (MCF-10A), further supporting the tumor-promoting role of HSPB1 in breast cancer." (PMID 37454220, 2023). "In addition, we also investigated the effect of HSPB1 on breast cancer metastasis in vivo using a pulmonary metastasis model." (PMID 37454220, 2023). "Notably, HSPB1 is involved in breast cancer cell lines proliferation, and HSPB5 is associated with breast carcinoma progression, making HSPB5 a biomarker for the diagnosis of breast cancers." (PMID 36765939, 2023). "Similarly, it was found that downregulation of HSP27 (HSPB1) in MCF-7 human breast cancer cells upregulates PTEN, which is responsible for apoptosis." (PMID 34578333, 2021). "Overexpression of HspB1, HspB2, and HspB5 inhibits apoptosis in breast cancer cells." (PMID 32927696, 2020). "Similarly, knockdown of HspB1 decreased doxorubicin resistance of breast cancer cells and 17-AAG resistance of cervical cancer cells." (PMID 32927696, 2020). "Additionally, HspB1 (along with Hsp70) is upregulated in radioresistant CSC-like SP cells isolated from breast cancer cells." (PMID 32927696, 2020). "Similarly, HspB1 was identified to regulate vasculogenic mimicry activity in CD24−CD44+ALDH+ breast cancer stem cells." (PMID 32927696, 2020). "This locus of 4 bp deletion in intron 2 of Hspb1 gene showed not-significant association with mammary tumor in cats." (PMID 28224005, 2016).
breast cancer (continued). "One mammary tumor sample‏ (CP7) showed down-regulation of Hspb1 as compared‏ to the calibrator, which showed fold change of 0.42.‏ Down-regulation might be associated with homozygous‏ locus of 286A>G, 305T>C and 338C>T." (PMID 28959337, 2016). "Back in 1997, a direct correlation between elevated level of HspB1 in the later stage of tumor progression and the invasive and metastatic potential of human breast cancer cells was confirmed in vivo in an assay measuring the number of lung metastases in mice injected with HspB1-transfected cells." (PMID 24514166, 2014). "Besides the MTA-3 pathway (ZR75-1), HSPB1, an ATP-independent chaperone with the hsp20-like chaperonedomain, operates in multiple pathways like the breast cancer estrogen signaling pathway (MCF-7, ZR75-1)." (PMID 17883861, 2007). "HSPB1 also binds to Ikβ-α and promotes its ubiquitination-mediated degradation, leading to increased nuclear translocation and activation of the NF-κB signaling pathway, with novel functional roles in regulating chemoresistance and ferroptosis in breast cancer." (PMID 39392831, 2024). "Therefore, we further investigated whether HSPB1 could regulate the anti-cancer activity of doxorubicin through modulating ferroptosis in breast cancer cells." (PMID 37454220, 2023). "However, the detailed role of HSPB1 mutation in breast cancer has not been reported, and more research is needed in the future." (PMID 37454220, 2023). "Therefore, we speculate whether HSPB1 regulates ferroptosis through NF-κB signaling pathway in breast cancer." (PMID 37454220, 2023). "We further examined whether HSPB1 regulated the ubiquitination of Ikβ-α in breast cancer cells." (PMID 37454220, 2023). "Furthermore, HSPB1 antibody levels are elevated in patients with breast cancer." (PMID 37268925, 2023). "Therefore, we propose HSPB1 as a marker of poor survival in patients with breast cancer." (PMID 37268925, 2023). "We hypothesized that HSPB1 is involved in breast cancer metastasis." (PMID 37268925, 2023). "However, the effect of HSPB1 on the progression and chemoresistance and the underlying mechanism in breast cancer has not yet been fully explored." (PMID 37454220, 2023). "Interestingly, amplification is the major type of mutation, and it might be responsible for the upregulated expression of HSPB1 in breast cancer." (PMID 37454220, 2023). "In addition, the inhibitory effect caused by HSPB1 knockdown could be reversed by the knockdown of IKβ-α in breast cancer cells, which further demonstrated that HSPB1 regulated the aggressive behaviors of breast cancer cells through NF-κB activity." (PMID 37454220, 2023). "In addition, our results also revealed the doxorubicin-mediated upregulation of HSPB1 in breast cancer, indicating that HSPB1 might be involved in the regulation of doxorubicin-induced ferroptosis." (PMID 37454220, 2023). "We also investigated the role of HSPB1 in paclitaxel (PTX)-induced ferroptosis, which is another frequently-used chemotherapeutics for breast cancer patients." (PMID 37454220, 2023). "Several known proteins (including HSP90AB1, HSPB1, LDHA, ENO1, PGK1, KRT18, and AKR1C2) and pathways were observed between model breast cancer cell lines related to hormone response, cell metabolism, and cell morphology." (PMID 36937585, 2023). "Overall, IL6 showed a significant role in the HSPB1-mediated malignant behaviors, and it is possible that HSPB1 is involved in the regulatory function of IL6 through modulating NF-κB activity in breast cancer." (PMID 37454220, 2023). "Consistently, HSPB1 knockdown inhibited cell growth, migration, invasion, and EMT in breast cancer cells." (PMID 37454220, 2023). "Here, we identified novel functional roles of heat shock protein beta-1 (HSPB1), regulating chemoresistance and ferroptotic cell death in breast cancer." (PMID 37454220, 2023).
breast cancer (continued). "Our results revealed that HSPB1 overexpression promoted the secretion of IL6, whereas HSPB1 knockdown led to decreased IL6 secretion in breast cancer cells." (PMID 37454220, 2023). "HSPB1 or HSP27 is an eminent candidate of sHSPs family which has been extensively studied in many cancers, including breast cancer, endometrial cancer, lung cancer, liver cancer andprostate cancer." (PMID 31540420, 2019). "Finally, among the upregulated small heat shock proteins, HSPB1 stands out as the highest expressed of the group and appeared upregulated in Luminal A, Luminal B, and HER2 (close to the cut-point in Basal); the protein encoded by this gene has been well studied in breast cancer." (PMID 29954368, 2018). "Therefore, we further investigated the effect of HSPB1-induced IL6 in the progression and immune infiltration of breast cancer." (PMID 37454220, 2023). "In addition, HSPB1 overexpression led to enhanced secretion of IL6, which further facilitated breast cancer progression." (PMID 37454220, 2023). "We, therefore, speculate that ANXA2, HSPB1, and TIMP1, may be among the genes induced by ZEB1 during early/partial EMT stages that may change the tissue tropism of ERα+ breast cancer cells." (PMID 35440541, 2022). "Additionally, the contribution of HspB1 to cell migration, invasiveness, and EMT was found in several CSC-related studies, including breast cancer and salivary adenoid cystic carcinoma." (PMID 32927696, 2020). "Indeed, several studies have shown that HspB1 is essential for CSC stemness in salivary adenoid cystic carcinoma, non-small-cell lung cancer, and breast cancer." (PMID 32927696, 2020). "Heat shock protein beta-1 (HSPB1) binding to Ikβ-α and promoting its ubiquitin-mediated degradation can lead to the activation of NF-κB signal transduction, and inhibition of ferroptosis can upregulate the expression of HSPB1, thereby promoting the resistance to breast cancer treatment drugs." (PMID 41226498, 2025). "Our study highlights HSPB1 as a novel regulator of chemoresistance in breast cancer, providing the potential that targeting HSPB1 might be a novel strategy to prevent breast cancer progression and overcome therapy resistance." (PMID 37454220, 2023). "However, the clinical value and function of HSPB1 in breast cancer has not been extensively explored." (PMID 37268925, 2023). "Despite these observations, a comprehensive study of HSPB1 in breast cancer has not yet been conducted, and it remains unclear how HSPB1 affects breast cancer occurrence and development." (PMID 37268925, 2023). "The results showed that the addition of IL6 neutralizing antibodies could abrogate the enhanced effect of supernatants from HSPB1 overexpressing cells on THP1 migration, suggesting the involvement of HSPB1-IL6 pathway in the regulation of accumulation of macrophages in breast cancer." (PMID 37454220, 2023). "MCF10A cells exhibited significantly increased expression of HSP90AA1, CARHSP1, HSPA12A and decreased expression of HSPB1, HSPBL2, HSPA6, and HSPA7 (C vs H), while the three breast cancer lines showed no significant 2-fold or greater alterations in the expression of these genes (C’ vs H’)." (PMID 24511912, 2014).